CD44 (CD44 molecule (IN blood group))
Diseases named in the same sentence as CD44 in open-access papers (continued):
Sharing a sentence is not in itself a finding about the gene and the disease.
infection (continued). "We therefore investigated whether the intranasal or intramuscular infection with NY-ESO-1 S-FLU virus differentially induced the expression of the molecules (VLA-1 [CD49a], CXCR6, CD103, CD44, CD49d, CCR5 and CXCR3) implicated in retention or trafficking of effector CD8+ T cells in lung." (PMID 36626205, 2023). "To determine the type of cellular response induced upon infection in the immunized mice and controls, we evaluated the expression of the transcription factors T-bet, GATA-3 and RORγt, respectively, associated with Th1, Th2 and Th17 cell populations in antigen-experienced (CD44+) CD4+ T cells." (PMID 35746533, 2022). "Furthermore, the effects of CD44 on PEDV infection were visualized by IFA." (PMID 34515624, 2021). "Therefore, another mode of HIV-1 spread in SLOs could be FRC-mediated trans-infection, in which virion-incorporated CD44 serves as an essential factor." (PMID 34696365, 2021). "In addition to chemotaxis, adhesion molecules such as ICAM-1, CD11b, and CD44 could be mediating CCR2+Ly6C+ monocyte trafficking to sites of infection as it was shown in the liver of primary Lm-infected mice." (PMID 34516896, 2021). "Additionally, we found that WT and ΔMHCIi infection resulted in a similar relative abundance of B819-26-specific CD8+ T cells with a memory phenotype (CD44+CD62L+KLRG1-CD127+) at 25 dpi, suggesting that viral MHCI inhibition does not affect memory T cell development." (PMID 29444189, 2018). "The concomitant downregulation of CD27 on NKG2D-positive γδ T cells as well as the upregulation of CD44 further supports the view that the majority of the γδ T-cell population persists in an effector/memory state even after resolution of the acute phase of the infection." (PMID 25658831, 2015). "Early IFNAR blockade did not significantly affect total numbers of neutrophils, total MDMs, or CD44+CD62L−CD4+ T cells in lungs, but Ly6C−MHC-II+ MDM numbers were increased at 20 days after infection, mirroring results in C57BL/6 mice." (PMID 40986319, 2025). "We found that the antigen-experienced (CD44+) and short-lived effector (CD127lowKLRG1high) CD8+ T cell numbers were significantly reduced throughout the infection." (PMID 39229137, 2025). "We found that, at both day 5 and day 10 post-infection, there was a significant reduction in the frequency of CD44+ CD25+ POSH cKO CD8 T cells compared to CD44+ CD25- POSH cKO cells." (PMID 40672960, 2025). "We found that at 5 days post infection (dpi), there was a clear effector CD4+ T cell (CD44+) population emerging while the majority of CD4+ T cells were still of naive phenotype (CD44–) (left)." (PMID 40777021, 2025). "Accordingly, in this study, the transdifferentiated neutrophil subset (P2/P5) infected by AG83 exhibited the highest expression of phagocytic marker CD44, further consolidating the role of CD83 in promoting infection." (PMID 40340446, 2025). "We found that while blood eosinophil counts quickly and dramatically dropped after the infection with SARS-CoV-2, their phenotype changed into CD69/CD125/CD63high and CD44/CCR3low." (PMID 40710346, 2025). "The expression of CD44, a marker that distinguishes memory from naïve CD8 T cells, remained low on P14 cells post-transfer compared to infection-induced LCMV-specific memory CD8 T cells, indicating that P14 cells housed in B6 mice retained a naïve phenotype." (PMID 41279312, 2025). "This was accompanied by markedly increased total and CD44+ CD62L− CD4+ T cell numbers in lungs of C57BL/6 than C3HeB/FeJ mice by 28 days after infection with 6C4 or 4I2." (PMID 40986319, 2025). "The upregulation of the Wnt target gene expression, including Axin2, EPHB2, CCND1, CD44, TERT, and MYC in PEDV-infected cells, further highlights the activation of WNT signaling in response to infection." (PMID 40396761, 2025). "Following the infection, WC1+ γδ, NK, CD4-CD8+, CD4+CD8-, CD4+CD8+ T cells and NK cells all exhibited a significant increased percentage of the CD44 High phenotype." (PMID 41573562, 2025).
infection (continued). "The proportion of IL-2 and IFN-γ secreted by CD4+CD44+ and CD8+CD44+ T cells in the vaccine immunization group exhibited a significant increase compared to the PBS + infection and CpG + infection group." (PMID 40266142, 2025). "Previous studies have shown that CD44 is essential for the life cycles of various pathogens, such as HCV, HIV-1, and HBV, facilitating their infection." (PMID 40544280, 2025). "We found that antigen-experienced CD8 + T cells (CD49d+CD44+) accumulated within the CD8 + T cell compartment; this accumulation began to level off at ~60% of the total CD8 + T cells by >5 weeks post infection." (PMID 40720547, 2025). "CD44 blockade also markedly decreased GPNMB+CD11c+ and F4/80+ macrophage infiltration at 49 days after infection." (PMID 39052353, 2024). "On the other hand, peptides 3–6 showed an elevated subpopulation of CD44+ and IL-2+ within CD4+, and CD3+ populations after 4 days of infection." (PMID 38629077, 2024). "Following infection, PEP-619WW had a higher frequency of Th1 cells, determined by CD44 and Tbet positive cells." (PMID 38512979, 2024). "Our approach is based on the detection in isolated hemocytes from G. mellonella hemolymph of cell membrane markers typically expressed by human immune cells upon inflammation and infection, for instance CD14, CD44, CD80, CD163 and CD200." (PMID 38191588, 2024). "Cell membrane markers typically expressed on monocytes/macrophages upon inflammation/infection (CD14, CD44, CD200), M1-polarization (CD80) and M2-polarization (CD163) were analyzed in the hemocyte population isolated." (PMID 38191588, 2024). "Restimulating mice with S. pneumoniae 6 weeks after primary infection with S. pneumoniae resulted, as expected, an increase in lung CD4+/CD44+/CD62L+ TcM 24 h later, but reduced numbers of CD4+/CD44+/CD62L-/CD27+ effector T cells and their expression of CD103." (PMID 38773113, 2024). "Results derived from flow cytometry indicated that the populations of effector memory T cells, i.e. CD44+ CD62-, were increased in both mice at 4 weeks post-B.1.351 β infection when compared to the mock-infected controls." (PMID 39475775, 2024). "At day 14 p.i., we sorted CD45.1+CD45.2+CD44+Tigit+IL-7Rα–PD-1+CXCR5+ and CD45.1+CD44+Tigit–IL-7Rα+PD-1+CXCR5+ CD4+ T cells and co-transferred them into CD45.2+ recipient mice followed by PR8 infection." (PMID 37330549, 2023). "Flow cytometry data show that the presence of B19V DNA did not alter the specific MSC markers’ expressions (such as CD29, CD44, CD73, CD90 and OCT4) after 9 days of infection compared to the phenotype of uninfected cells." (PMID 37175911, 2023). "WT mice also display increased FoxP3+ cell frequencies amongst CXCR5+CD44+CD4+ T cell populations one week post infection compared to μMT animals, suggesting B cells promote TReg development amongst CXCR5+CD44+CD4+ T cells during Brucella infection." (PMID 37721965, 2023). "Upon introduction of CD127 to determine T‐bet expression in effector cells (CD44+CD127−), pup effector CD4+ T cells expressed significantly higher levels of T‐bet after infection." (PMID 36131528, 2022). "At weeks 4, 6, 8 and 10, the percentage of CD4+ effector memory T cells (Tem, CD44+CD62L-) was higher than that of the control group, and it was significantly increased at week 4 and represented 93.04% of CD4+ T cells after infection." (PMID 36046744, 2022). "Vhl cKO mice showed a high frequency of CD44 + CD62L + central memory CD8T cells (TCM) in lungs before and during infection, while CD4 TCM were only increased in Vhl cKO at 8 weeks after infection." (PMID 36064840, 2022). "Phenotypically, CD8+ TILs of Cd47−/− mice showed a significant decrease of CD44+ effector phenotype and a concomitant increase of CD62L+ phenotype, consistent with our finding in the context of LCMV Cl13 infection." (PMID 36105746, 2022). "High amounts of CD44+ and CD69+ T-lymphocytes are present in both lymphatic organs in the early phase of infection." (PMID 34202636, 2021).
infection (continued). "TEM cell populations expressing PD-1, CD44, and CD11a and either CD27hi (Sp cluster 2) or CX3CR1 (Sp cluster 4) were dominantly present in LCMV clone 13 infection." (PMID 33458613, 2021). "First, we performed scRNA-seq on GP33+ CD44+ CD8+ cells from spleen lymphocytes and siIELs 30 days post-LCMV ARM infection." (PMID 34440912, 2021). "CD44 is a trans-membrane glycoprotein highly expressed on multiple immune cells which is involved in regulating inflammatory response during ALI and infection." (PMID 34016170, 2021). "Cytosplore analysis of the GP33-specific CD8+ T cells using the cell surface markers CD44, KLRG1, and CD62L revealed substantial differences in the phenotype of the GP33-specific CD8+ T cells between the three different infections." (PMID 33458613, 2021). "Upon infection, both WT and CD40L-/- mice show an increase in the numbers of CD4+ T cells, CD4+ CD44+ effector CD4+ CD25+ Foxp3+ Tregs compared to their respective MI." (PMID 34898656, 2021). "CD44 is augmented in BALF, indicating that bone marrow-derived neutrophils change the expression of surface markers in response to infection, even when they are intranasally delivered and come from the bone marrow." (PMID 33995357, 2021). "The proportion of TH2 (CD4+ CD44+ FoxP3- Tbet- GATA3+) cells was significantly lower than the TH1 cells, and ranged from 4% - 11% of the activated CD4+ T-cells in the UgCl223 infection." (PMID 35186781, 2021). "We observed BAL cells expressing the activation marker CD44 and surface markers specific for T lymphocytes (CD4 and CD8) on day 7 post-infection." (PMID 34359982, 2021). "Along with this increase in the frequency of CD44+ memory T cells, mice from CC-RIX lines with low viral titers at day 2 post-infection had a significantly increased frequency of baseline splenic Foxp3+ regulatory T cells (Treg)." (PMID 33513210, 2021). "These CD69+ CD4+ T cells up-regulated CD44 and CD103 expression over time after infection, indicating that BALB/c mice were able to induce TRM cells in the nasal tissue after Bp infection." (PMID 33420041, 2021). "After infection, TSf-ISPA-vaccinated and 5FU-treated mice showed a marked increase of the CD8 response, which included an increased expression of CD107a and CD44 markers in CD8+ cultured splenocytes." (PMID 34295832, 2021). "Ninety percent of the CD4 and 60–70% of the CD8 brain T cells showed a CD44+KRLG1- memory phenotype during the early and late stages of infection." (PMID 34587172, 2021). "On day 8 post LCMV-Armstrong infection, Mettl3fl/flCd4-Cre mice-derived CD4+ T cells had much lower cell numbers of CD44+CXCR5+ TFH cells than those of competitor bone marrow-derived CD4+ T cells." (PMID 33637761, 2021). "Of note, HA present on the surface of CD44-expressing CD4+ T cells prevents direct binding and infection of CD44-containing HIV-1." (PMID 32752131, 2020). "During infection, both CD4+ and CD8+ T cells became activated, as was shown by a downregulation of CD62L expression and an upregulation of CD44 expression, which corresponded with a Teff phenotype." (PMID 33664739, 2020). "Upon vaccination but prior to infection, CD4+CD44+ T-cell numbers generally increased in all organs, when compared to the numbers in naïve mice." (PMID 32545304, 2020). "The results demonstrate that during both experimental infection of bovine mammary glands with LPS or MDP, apoptosis of lymphocytes was induced in the initial phase of the inflammatory response and CD44 was also overexpressed at the beginning of inflammation." (PMID 32517153, 2020). "TB10.44−11-tetramer-binding CD8 T cells constituted ~1/3 of the total CD44+ CD8 T cells and showed a distinct accumulation early after infection." (PMID 33193338, 2020). "During the four days following the infection, the CD44, SOX2, NANOG, and OCT4 levels have changed significantly at p ≤ 0.001 with respect to duration of infection." (PMID 33093503, 2020).
infection (continued). "Both CD4 and CD8 T cells showed similar frequency in WT and IL16 KO mice after MHV68 infection, however, IFN-γ-expressing Th1 subset of CD4 T cells and CD44+ activated CD4 T cells were dramatically increased in IL16 KO mice as compared to WT mice." (PMID 32735617, 2020). "Five days post-infection, the P14 cells detected in WT and IL4I1-/- mice expressed similar levels of the activation marker CD44, but their expansion was markedly lower in IL4I1-/- mice." (PMID 33343572, 2020). "CD44 expression was up-regulated in dose-dependent fashion, whereas CD24 was not significantly changed, revealing a CD44+/CD24−/low phenotype following infection." (PMID 33233485, 2020). "Also during infection, CD44 may influence host defense by affecting phagocytosis." (PMID 31749827, 2019). "At D21 post-infection, MM increased in Mtb-specific TB10.4-TET+ cells and in total CD44+ CD8+ T cells from BCG-infected mice; this effect was abrogated by D35 in BCG but was sustained in TB10.4-TET+ cells." (PMID 31825836, 2019). "IFN-γ production increased in total and TB10.4-TET+ CD44+CD8+ effector T cells from Mtb-infected mice compared with CD44+CD8+ T cells from UI and BCG-infected mice at D21 and D35 post-infection." (PMID 31825836, 2019). "At 45 h post-infection, Smarta CD4+ T cells of both genotypes underwent two to three divisions, divided at similar rates, and showed similar levels of CD44 induction." (PMID 30575739, 2018). "When analyzed during memory stage after 40 dpi, H-2Kb-SIINFEKL-specific CD8+ T cells were heterogeneously stained for CD44, CD62L, and IL-7R, a phenotype distinct from those of memory cells generated during persistent MHV68 infection." (PMID 30388704, 2018). "This memory T cell subset is established late during resolution of primary infection of those tissues, has a distinct genetic signature, and is often defined by the cell surface expression of CD69, CD103, CD49a, and CD44 in both mouse and human studies." (PMID 29632527, 2018). "In the lungs, only sequential infection resulted in a moderate but significant increase of memory T cells and this effect was restricted to CD8+CD44+ T cells." (PMID 30356772, 2018). "Thus, it is likely that whereas HA molecules bound to CD44 incorporated into virus particles promote binding to FRCs and thereby trans-infection, these virus-associated HA molecules would not participate in direct binding to target T cells unless T cell surface HA is removed or downregulated." (PMID 29934525, 2018). "T cell activation, as measured by the downregulation of CD62L expression in CD44+CD4+ T cells, was reduced early during infection, and restored to WT levels at the later stage." (PMID 29675017, 2018). "At day 20 post-infection, LCMV Arm and LCMV Cl-13 infected mice had approximately equal percentages of activated (CD44+) GP33-specific CD8 T cells (left subplots)." (PMID 29317703, 2018). "Expression of the activation and effector function markers CD69, CD160, CD44, and CD62L were analyzed at day 6 post infection (p.i.)." (PMID 28261571, 2017). "This systematic approach revealed that CD81, CD44, CD98, caveolin-1 and catenin delta-1 were down-regulated during infection whereas GRP-78 was up-regulated." (PMID 29121670, 2017). "Interrupting IL-4Rα expression prior to the secondary infection resulted in reduced proportions and total numbers of CD4+CD44+ T cells expressing Gata-3 compared to control mice given vegetable oil." (PMID 28651009, 2017). "Infection of cells with low MOI of Lenti-141 (that is, 2.5 and 5) similarly reduced CD44 mRNA levels (b right)." (PMID 28112170, 2017). "During infection, CD8+ T cells in perigonadal fat expressed an effector phenotype (CD8+ CD44– CD69+) that was also seen in the lung where, in addition, CD4+ T cells with similar characteristics were identified." (PMID 29040326, 2017).
infection (continued). "Zebrafish (Danio rerio) CD44 and CD154 were significantly up-regulated after stimulating with KLH, while CD36 was down-regulated during infection of Mycobacterium marinum." (PMID 28738780, 2017). "While comparable frequencies of pulmonary CD4+ T cells were present between the two strains at 90 days post-infection, the frequencies of pulmonary CD4+CD44+ T cells were reduced in p55∆NS mice." (PMID 27995986, 2016). "In contrast, we detected a higher percentage of CXCR6 seven days after infection and of CD11c at all-time points in the CD8+ CD44+ TEM cells compared to the control group." (PMID 27272720, 2016). "Our data shows the frequency of CD4+ RTEs expressing the activation marker CD44 increases significantly in L. donovani-infected animals, suggesting that CD4+ RTEs are at least partially activated during an ongoing infection." (PMID 27658046, 2016). "Protected mice received an intranasal B. pertussis challenge 56 days after the primary infection (D0) and showed increased percentages of IFNγ- and IL-17A-producing Prn-specific CD4+ CD44+ T-cells on 10 days p.c. compared to the percentage in naive mice." (PMID 27711188, 2016). "When analyzing the expression of the selected homing molecules in the activated TEM cell subset, there was a higher percentage of CCR5, CCR2 and CD11c in the CD4+ CD44+ TEM cells at 10 and/or 14 days post-infection than in the control group." (PMID 27272720, 2016). "LM-OVA infection led to CD44 upregulation in both CD4+ and CD8+ splenic T cells as the spleen is the primary site of infection." (PMID 26583325, 2015). "The infection with both Salmonella serovars led to an increase of the macrophage antigen expression of MHC class I at 24 and 48 hpi as well as of MHC class II and CD44 at 4, 24 and 48 hpi." (PMID 25811871, 2015). "Since OPN-levels were unchanged upon 2-20 infection, we examined CD44, a known receptor for OPN; in a pattern similar to that of OPN, CD44 was increased upon 2-20 RSV infection and gradually returned towards baseline expression in young mice." (PMID 24558422, 2014). "Expression of the early astrocyte marker CD44 increased ∼2-fold with both HOPX and NFIX overexpression in fetal astrocytes (assayed three days post-infection)." (PMID 24848099, 2014). "To investigate this further, we examined a panel of T cell activation markers (CD62L, CD69, CD44, CD25) and homing receptors (CCR5, CXCR3, CCR7) at days 5, 6 and 7 post-infection." (PMID 24809749, 2014). "Leukocytes in lymph nodes from infected and non-infected WT, PMN-depleted and Genista mice were analyzed by flow cytometry at 8 and 15 days of infection using CD4+/CD44+, CD8+/CD44+, B220+/CD95+, and CD11b+/Ly6C+ cell markers." (PMID 23458832, 2013). "The expression of CD44 and CD40L in the CD4+ and CD8+ T cells was gradually up-regulated post-infection, while the expression of CD62L was down-regulated (middle and lower)." (PMID 23555767, 2013). "At week 8 post-infection, we analysed CD200 and CD200R expression in T cells from the mesenteric LN (MesLN) together with CD44 to distinguish Ag-primed (CD44hi) from naïve (CD44lo) cells." (PMID 22496920, 2012). "At 72 hours post infection, the virus titer in CD44+CD24+ESA+ cells was approximately fifteen times higher at MOI 0.01, and ten times higher at MOI 10 in comparison to CD44+CD24-ESA+ cells." (PMID 22901246, 2012). "The surface expression of LFA-1, LFA-3, CD44, CD24, and in particular of CD62L molecules, was induced after VV and VV:ΔHA infection of HeLa cells (unpublished results)." (PMID 21901096, 2011). "To assess this, at day 5 after MAb treatment (day 9 after infection), we profiled Db-NS4B-tetramer+ CD8+ T cells for expression of PD-1, CTLA-4, CD43, CD44, CD127, and CD11a." (PMID 22144897, 2011). "We also determined that the DP cells released from thymus during the organ atrophy showed a characteristic profile of CD44 and CD69 expression similar to single-positive T cells differentiated upon infection with T. cruzi." (PMID 21858238, 2011).